REN (renin)
Diseases named in the same sentence as REN in open-access papers (continued):
Sharing a sentence is not in itself a finding about the gene and the disease.
Obesity (continued). "HTN develops through a multifaceted interaction of biological systems like the sympathetic nervous system, the renin–angiotensin–aldosterone system (RAAS), vascular resistance, and endothelial function, alongside lifestyle factors such as obesity, high salt intake, inactivity, and alcohol use." (PMID 40142222, 2025). "Angiotensin 1–7 (Ang 1–7), a component of the renin-angiotensin system (RAS), exhibits anti-inflammatory effects in obesity and related disorders, though its mechanisms remain unclear." (PMID 39803918, 2025). "The positive correlation between pulse pressure and plasma renin which we observed in the subpopulation of boys with either obesity or T1DM, does not provide an answer on which of these 2 actors triggers the other." (PMID 36996194, 2023). "To investigate these hypotheses, a clinical study was set up in which we included children and adolescents with either T1DM or obesity, and analysed urinary EGF and serum renin in relation to blood pressure parameters." (PMID 36996194, 2023). "The Renin–Angiotensin–Aldosterone System (RAAS) has a major role in the regulation of blood pressure, hydrosaline metabolism, autonomic pathways and neuroendocrine systems, and its excessive activation is observed in obesity, hypertension and heart failure." (PMID 37794395, 2023). "Aiming at dissecting a hypothetical interaction between systemic blood pressure, plasma renin and urinary EGF in children, we compared the characteristics of these three actors in two distinct paediatric populations, namely children with obesity and T1DM, thereby avoiding any overlap of disease." (PMID 36996194, 2023). "Db/db mice, characterized by obesity and T2DM, and juxtaglomerular (JG) cells, which line the afferent arterioles at the entrance of the glomeruli to produce renin, treated with glucose, palmitic acid (PA) and oleic acid (OA), were used as animal and cellular models." (PMID 36675205, 2023). "The renin–angiotensin–aldosterone system (RAAS), the activation of the sympathetic nerve, hyperleptinemia, obstructive sleep apnea (OSA), and so on all participants in the occurrence of obesity LVH." (PMID 35081909, 2022). "However, few studies have experimentally examined the role of renin–angiotensin system blockers and calcium channel blockers (CCB) in obesity." (PMID 36145135, 2022). "The renin-angiotensin-aldosterone system (RAAS) exerts an important impact on the cardiovascular system by participating in the pathogenesis of different pathological scenarios, including hypertension, diabetes and obesity." (PMID 33800427, 2021). "Furthermore, the renin–angiotensin–aldosterone system (RAAS), which is usually over-activated in patients with obesity, has been connected with SARS-CoV-2 infection." (PMID 34960696, 2021). "Renin-Angiotensin System (RAS) signaling pathway: a research shows that erucin is a bioactive compound isolated from broccoli, known as a Ras inhibitor, and has potent anti-obesity efficacy by inhibiting adipogenesis of 3T3-L1 cell line." (PMID 34889899, 2021). "The exact mechanism of vascular dysfunction in obesity is still not well clarified; however, there are some pathways such as renin–angiotensin–aldosterone system (RAAS) disorders and PVAT-derived factors’ dysregulation, which are involved in the process." (PMID 34836100, 2021). "The possible role of PRA in the characterization of metabolic phenotype of “remitted obese” is supported by investigations on mice lacking renin (Ren1c), a strain prone to diet-induced obesity." (PMID 34107965, 2021). "Angiotensin converting enzyme (ACE) is well-known for its role in blood pressure regulation via the renin–angiotensin aldosterone system (RAAS) but also functions in fertility, immunity, haematopoiesis and diseases such as obesity, fibrosis and Alzheimer’s dementia." (PMID 33146371, 2020).
Obesity (continued). "We did however reveal specific associations of aldosterone, and not renin, with VLDL particles, linoleic acid metabolism, and urate, which provide novel clues about the pathogenic effects of aldosterone in obesity." (PMID 32529242, 2020). "First, it has been reported that the renin knockout mice are lean, insulin sensitive, and resistant to diet-induced obesity without changes in food intake due to a higher metabolic rate and gastrointestinal loss of dietary fat5." (PMID 26732252, 2016). "A previously published paper from our group shows an impaired renin secretion after hemorrhage in obesity, suggesting an impaired renal SNA in an animal model of obesity, suggesting regional differences in SNA in obesity." (PMID 25472607, 2014). "The present study aimed to compare the effect of blockades, using a direct renin inhibitor, an ACE inhibitor, and an AT1R antagonist, at different points in the RAS on glucose intolerance and pancreatic injury in a mice model of insulin resistance and obesity." (PMID 23894285, 2013). "Angiotensinogen, renin (or peptides with renin-like activity), angiotensin converting enzyme (ACE), and AT1 and AT2 receptors are all secretory products of the rodent adipocyte, and the expression of some are increased in obesity." (PMID 22475205, 2012). "A growing body of evidence shows that obesity can drive the progression of CKD and that the pathophysiological mechanisms are multifaceted, including altered hemodynamics, systemic inflammation, oxidative stress, and activation of the renin-angiotensin-aldosterone system (RAAS)." (PMID 40959557, 2025). "These conditions are promoted by visceral white adipocyte tissue dysfunction through chronically elevated pro-inflammatory adipokines (compared to people without obesity), oxidative stress, renin–angiotensin–aldosterone system activation, and an adverse gut microbiome." (PMID 40732953, 2025). "While still a relatively new area of investigation, recent studies suggest the renin–angiotensin system (RAS) may provide an ideal hormonal target to engage ARC neurocircuits to improve energy balance in obesity without elevating blood pressure." (PMID 34208939, 2021). "Obesity, in particular visceral obesity, is associated with mild activation of the SNS and increased sympathetic nerve activity may in turn increase renal sodium reabsorption and renin release, even without evident effects on kidney perfusion." (PMID 38186879, 2024). "Although reductions in renin are not obligatory for the reduction in BP during BAT, our simulations suggest that the renin-angiotensin system may still play some role in the efficacy of BAT in obesity." (PMID 34793497, 2021).
heart failure (417 papers, 2008 to 2026). Inability of the heart to pump blood at an adequate rate to meet tissue metabolic requirements. "While the renin‐angiotensin system (RAS) is implicated in heart failure pathogenesis, the causal contribution of angiotensinogen (AGT), the unique precursor of the RAS, to HFpEF remains undefined." (PMID 40888605, 2025). "Although there is strong evidence that inhibition of the renin-angiotensin-aldosterone system has beneficial effects on the prognosis of proteinuria, diabetic nephropathy, and heart failure, hyperkalaemia is a major cause of RAASi discontinuation." (PMID 38404365, 2024). "This renders the pancreas susceptible to injury in heart failure, where renin-angiotensin overactivation is a central feature underlying the pathophysiology." (PMID 35887892, 2022). "As heart failure becomes more severe, blood pressure lowers and renal perfusion worsens, causing baroreceptor and renin–angiotensin–aldosterone system activation, respectively." (PMID 35327416, 2022). "A hallmark of heart failure is chronic activation of the renin-angiotensin-aldosterone system, especially marked by a systemic increase in levels of angiotensin-II, a peptide with pleiotropic activities." (PMID 34281199, 2021). "CKD is common in heart failure (HF) and associated with morbidity and mortality, yet life-prolonging medications such as renin-angiotensin-aldosterone inhibitors (RAASi) are underused due to risk of hyperkalaemia." (PMID 34229607, 2021). "In conclusion, we successfully generated a heart failure mouse model which has cardiac hypertrophy and higher mortality with increased susceptibility to human renin inhibition." (PMID 32056390, 2020). "Heart failure (HF) is characterized by cardiac dysfunction along with autonomic unbalance that is associated with increased renin-angiotensin system (RAS) activity and elevated levels of proinflammatory cytokines (PICs)." (PMID 27746855, 2016). "Heart failure is associated with activation of the renin-angiotensin-system and it is well-established that ANG-II induces cardiac injury partially through increased generation of ROS." (PMID 22693564, 2012). "In addition to hemodynamic disturbances, increased neurohormonal activation through the sympathetic nervous system and the renin-angiotensin system is also associated with the progression of heart failure." (PMID 40535150, 2025). "Aberrant renin-angiotensin-aldosterone system (RAAS) signaling is a hallmark of heart failure." (PMID 38180450, 2024). "Furthermore, the “Biomarkers, risk factors, and prognosis prediction in heart failure” cluster was also divided into NT-proBNP, serum proteins, and the renin–angiotensin–aldosterone system." (PMID 39081280, 2024). "The associations of higher renin with lower sodium excretion supported our hypothesis and agreed with the existing evidence of poorer outcomes for heart failure patients with higher renin levels." (PMID 35620081, 2022). "Since using neprilysin inhibitor alone will increase angiotensin II level, therefore, combining sacubitril with either ACE inhibitors or renin inhibitors could provide further relief of neurohumoral changes associated with heart failure." (PMID 31053170, 2019). "Moreover, congestion can cause heart failure progression through further renin–angiotensin–aldosterone system (RAAS) and sympathetic activation, ventricular geometric changes, pulmonary hypertension, and other end-organ hypoperfusion." (PMID 31591412, 2019). "Similarly, elevated plasma renin concentrations have been associated with death due to heart failure." (PMID 30057603, 2018). "The PARADIGM-HF trial, conducted in 8442 patients with heart failure, confirmed that neprilysin inhibition (when added to renin-angiotensin system blockade) reduces hospitalization and death due to heart failure but probably has little effect on the risk of stroke or myocardial infarction." (PMID 28477314, 2017).
heart failure (continued). "Moreover, changes in the myocardial ECM is associated with the development of diastolic dysfunction in heart failure, even in the short term, possibly through the renin-angiotensin-aldosterone system (for review)." (PMID 23738044, 2013). "Hypoxia due to heart failure causes vasoconstriction of the afferent arterioles of the kidney, with consequent reduction in renal perfusion, activation of the renin–angiotensin–aldosterone system and production of antidiuretic hormone, causing plasma volume expansion and haemodilution." (PMID 21655315, 2011). "the correlation found between vitamin D, plasma renin activity and C-reactive protein suggests that an activated renin–angiotensin system and an altered cytokine profile may play an important role in the association between vitamin D and heart failure." (PMID 21135989, 2010). "AF itself may increase the risk of ESRD by multiple mechanisms, including renin-angiotensin-aldosterone system activation, volume retention, heart failure aggravation, renal artery thromboembolism, and decreased cardiac output and renal perfusion due to rapid/irregular ventricular rate." (PMID 37915744, 2023). "Agents acting on the renin–angiotensin system were under-prescribed in our sample, whereas angiotensin II receptor blockers and angiotensin-converting enzyme inhibitors are effective to reduce all-cause mortality and cardiovascular mortality in people at high risk of heart failure." (PMID 32751644, 2020). "Therefore, the blockade of the renin-angiotensin system by MRA might have promoted the favorable association with heart failure hospitalization in patients with HFpEF." (PMID 31225889, 2019). "Second, IR may activate the renin-angiotensin-aldosterone system, accelerate ventricular remodeling, promote water and sodium reabsorption, increase circulation capacity, and ultimately cause cardiac insufficiency." (PMID 31281548, 2019). "This study compared the clinical outcomes of patients with heart failure (HF) with improved EF (HFimpEF) based on the maintenance of sacubitril/valsartan (S/V) or transition to a renin–angiotensin system blocker (RASB)." (PMID 40870531, 2025). "Reduced ventricular function, renin–angiotensin system up-regulation, and sympathoexcitation are hallmarks of heart failure (HF)." (PMID 40395026, 2025). "Background/Objective: Sacubitril/Valsartan are a combination drug approved for heart failure treatment, known to enhance natriuretic peptide activity and inhibit the renin–angiotensin–aldosterone system (RAAS)." (PMID 41011135, 2025). "Since renin converts angiotensinogen into angiotensin I, it is likely that the children with heart failure also showed an increase in angiotensin I after administration of enalapril." (PMID 41155980, 2025). "In heart failure, decreased renal perfusion due to a reduced cardiac output and renal congestion due to RV dysfunction activate the renin‐angiotensin‐aldosterone system (RAAS) and sympathetic nervous system." (PMID 39531152, 2025). "Patients with heart failure often exhibit activation of the sympathetic nervous system and the Renin-Angiotensin-Aldosterone System (RAAS)." (PMID 40837364, 2025). "At hospital discharge, the percentage of patients receiving a renin–angiotensin–aldosterone system inhibitor and the percentage receiving triple heart failure therapy was 81.4% in the intervention group and 57.9% in the surgery group." (PMID 40390996, 2025). "Reduced ventricular function, up-regulation of the renin–angiotensin system and sympathoexcitation are hallmarks of heart failure (HF)." (PMID 40395026, 2025). "It is secreted by ventricular myocytes in response to volume or pressure overload to counteract the effects of the renin-angiotensin-aldosterone system and the sympathetic nervous system during heart failure." (PMID 41143176, 2025).
heart failure (continued). "Retinol also influences the renin–angiotensin system and exhibits anti-inflammatory properties; both of these factors are relevant to the pathophysiology of heart failure." (PMID 40941272, 2025). "Traditional heart failure medications also act on the renin-angiotensin-aldosterone system (RAAS), but their therapeutic effects are far from those of sacubitril/valsartan." (PMID 39512825, 2024). "Anemia causes hypoxia of tissues, subsequent vasodilation, and reduced peripheral resistance, which leads to stimulation of the renin-angiotensin system and adrenal sympathetic system, which ultimately retain water and sodium, resulting in heart failure." (PMID 38800267, 2024). "Our findings suggest that low uCl− is a marker of more advanced heart failure, activation of the renin–angiotensin–aldosterone system and is related to worse one-year outcomes." (PMID 38890417, 2024). "Fluid restriction has long been believed to benefit patients with heart failure by counteracting the activated renin–angiotensin aldosterone system and sympathetic nervous activity." (PMID 39063995, 2024). "Currently, the main approach for treating heart failure is to improve hemodynamics by regulating the renin-angiotensin-aldosterone system (RAAS) and the sympathetic nervous system (SNS), which includes positive inotropy, diuresis, and vasodilation." (PMID 39512825, 2024). "The study aimed to study the association between exposure to renin–angiotensin–aldosterone system (RAS) inhibitors or beta-blockers and outcome after aortic valve replacement in patients with aortic stenosis and heart failure." (PMID 38812477, 2024). "Elevated BNP levels can antagonize the activated sympathetic and renin-angiotensin-aldosterone systems, with higher serum BNP or NT-proBNP concentrations indicating an increased risk of myocardial remodeling and heart failure." (PMID 39834729, 2024). "Disease-specific treatment involves immunosuppression, while non-specific treatment includes the use of diuretics, beta-blockers, renin-angiotensin-aldosterone system inhibitors, etc., similar to the management of other types of heart failure." (PMID 38883113, 2024). "When signs of heart failure develop, standard treatment according to the newest guidelines and cardioprotection with an inhibitor of the renin-angiotensin system is indicated." (PMID 39583362, 2024). "CKD and heart failure are known to have synergistic effects due to the activation of the renin-angiotensin-aldosterone system, fluid overload, and sympathetic activation, which worsen the severity of both diseases." (PMID 38813289, 2024). "This inadequate blood supply triggers neurohormonal responses akin to other forms of heart failure, such as the activation of the renin-angiotensin-aldosterone system (RAAS), the adrenergic nervous system, and the excessive release of antidiuretic hormone." (PMID 39036265, 2024). "Mirroring this, the renin-angiotensin system also operates locally in the heart musculature, along with its systemic activation in heart failure patients." (PMID 37623681, 2023). "Hypokalemia and hyperkalemia in heart failure are common as a result of drugs used to treat renin-angiotensin-aldosterone system dysfunction and poor kidney function." (PMID 37791200, 2023). "The renin-angiotensin system (RAS) is the main target of neurohumoral therapy in heart failure with reduced ejection fraction (HFrEF) effectively reducing mortality." (PMID 37941680, 2023). "Natriuretic peptides play an important role in heart failure through their effects on vasodilation and natriuresis, leading to a decrease in the activity of the renin-angiotensin-aldosterone system." (PMID 37047444, 2023). "Hyperkalemia (HK) is a barrier to optimization of renin-angiotensin-aldosterone system inhibitor (RAASi) therapy in heart failure (HF) and chronic kidney disease (CKD)." (PMID 36658531, 2023).